CAV1 (caveolin 1)
Diseases named in the same sentence as CAV1 in open-access papers (continued):
Sharing a sentence is not in itself a finding about the gene and the disease.
breast carcinoma (continued). "Results elucidated that expression levels of CAV1, CAV2, CAVIN1, CAVIN2, and CAVIN3 were significantly lower in breast cancer tissues than in normal samples, while the expression level of CAVIN2 was correlated with advanced tumor stage." (PMID 34513683, 2021). "The statistical results showed that CAV1, CAV2, CAV3, CAVIN1, and CAVIN2 were significantly less expressed in breast cancer tissues than in normal ones." (PMID 34513683, 2021). "Taken together, ursolic acid hinders breast cancer growth and metastasis in vivo by suppressing glycolytic metabolism via activating SP1/Cav-1 signaling." (PMID 34568078, 2021). "Interestingly, an increasing number of reports have demonstrated that Cav‐1 regulates tumor–host interactions by promoting tumor progression, growth, metastasis, therapy resistance and cell survival in different cancer types such as breast cancer, lung cancer, bladder cancer, and prostate cancer." (PMID 33605506, 2021). "The results elucidated that the transcriptional levels of CAV1, CAV2, CAVIN1, CAVIN2, and CAVIN3 were significantly lower in breast cancer tissues than in normal samples." (PMID 34513683, 2021). "In breast cancer autocrine and paracrine TGF-β signalling have been shown to induce downregulation of the membrane protein caveolin-1 (Cav-1) in CAFs." (PMID 34831065, 2021). "To analyze the CSD mutant in a CAV1 null background, we knocked out CAV1 using CRISPR/Cas in a MDA-MB-231 breast cancer cell clone." (PMID 33833286, 2021). "Mechanically sensitive caveolin-1 activation induces the PI3K/Akt/mTOR signaling pathway to promote motility and invasive in vivo formation, and metastasis of breast cancer." (PMID 34540654, 2021). "For the human breast cancer cells MDA-MB-231, which express CAV1 endogenously, levels of this protein were reduced using specific short hairpin constructs." (PMID 32152405, 2020). "A recent report showed that LEF1 and multidrug resistance-related genes, such as ABCG2, VIM, and Cav1, are highly increased in docetaxel (DTX)-resistant MCF7 breast cancer cells, indicating that LEF1 is involved in multidrug resistance in cancer." (PMID 32933177, 2020). "Besides, it may be relatively easy to develop Cav-1-targeted drugs to inhibit breast cancer growth." (PMID 32528105, 2020). "For instance, in the metastatic breast cancer cell line MDA-MB-231, CAV1-dependent activation of Rac-1 is observed in spreading assays." (PMID 32152405, 2020). "However, it is unknown whether Cav-1 loss contributes to the aerobic glycolysis phenotype of Breast cancer stem cells (BCSCs) or not." (PMID 32528105, 2020). "The effect of treatment on the expression of Cav-1 in stromal cells related to the percentage of cells expressing ER and PR for breast and uterine samples and HER2 in breast cancer samples." (PMID 33195223, 2020). "Except for Cav-1, Cav-2 is also reported as a target of mi-RNAs in MDA-MB-231 and MT-1 breast cancer cell lines." (PMID 31759347, 2019). "The activation of Cav-1 and PI3K/Akt/mTOR signaling under low shear stress increases the MT1-MMP expression, invadopodia formation, and ECM degradation and promotes breast cancer cell motility and metastasis." (PMID 31759347, 2019). "When we knocked down liprin-α1 in HNSCC and breast cancer cells grown in two-dimensional cell culture, CD82 was located at the vesicle-like structures and showed partial co-localization with caveolin-1." (PMID 30005669, 2018). "Then we determined if CAV1 overexpression abrogated the anti-cancer and chemosensitizing effects induced by ADQ in breast cancer cells." (PMID 30333750, 2018). "The estimated half-life of HER2 was similar to CAV1 in NCIN87 gastric, BT474 and SKBR3 breast cancer cell lines." (PMID 30510281, 2018). "The results showed that CAV1 expression was significantly downregulated in the MDA-MB-231 and MCF-7 breast cancer cells, and was enhanced in their taxol-resistant counterparts." (PMID 30333750, 2018).
breast carcinoma (continued). "In a co-culture system, oxidative stress-induced autophagy correlated with caveolin-1 (CAV1) downregulation in CAFs and TIGAR overexpression in adjacent breast cancer cells." (PMID 30234009, 2018). "In order to further confirm the anti-metastatic role of Cav1 in BMDCs, we used the polyoma middle T (MMTV-PyMT) spontaneous breast cancer mouse model, which resembles the characteristics of human luminal breast cancer." (PMID 29212030, 2017). "In the dataset of 50 breast cancer lines TF expression clustered with higher levels of basal-marker vimentin, keratin KRT5/14 and caveolin-1 (CAV1) but lower levels of luminal-marker keratin KRT8/18, ERBB3 and ESR1." (PMID 28938620, 2017). "This was also the case for the breast cancer cell line MCF7, while for HT29(ATCC) cells, besides Methotrexate and Etoposide, Doxorubicin also increased CAV1 expression." (PMID 29340103, 2017). "These were the only two drugs that increased significantly CAV1 protein levels in the other colon cancer cell line DLD-1 and the breast cancer cell line MCF7." (PMID 29340103, 2017). "A previous study reported that Caveolin-1 gene silencing promoted the activation of PI3K/Akt dependent on Eralpha36 and the transformation of MCF10ACE in breast cancers." (PMID 28186985, 2017). "Here, we identified Cav-1 is mechanosensitive to LSS exposure, and its activation-induced PI3K/Akt/mTOR signaling promotes motility, invadopodia formation and metastasis of breast carcinoma MDA-MB-231 cells." (PMID 26919102, 2016). "For instance, the expression of caveolin-1 (CAV1), a potential oncogene involved in breast cancer pathogenesis, has been shown to be regulated by differential methylation of CGI shores, which are regions of lower CpG density that flank CGIs." (PMID 26404381, 2015). "Cav-1 was up-regulated in MDR colon cancer cells, adriamycin-resistant breast cancer cells and taxol- and gemcitabine-resistant lung cancer cells." (PMID 26431273, 2015). "CAV1 and FLOT1 were also shown to affect migration and invasion in porcine kidney epithelial cells and breast cancer." (PMID 26002553, 2015). "In this study, the relationship between caveolin-1 expression and the chemosensitivity of HER-2-positive breast cancer cells to T-DM1 was investigated." (PMID 26172389, 2015). "In contrast, reduced expression of Cav1 was observed in HNSCC LNM, correlates with breast cancer nodal metastasis and is prometastatic in malignant melanoma." (PMID 26474461, 2015). "In the present study, we showed that c-Src dependent Cav-1 phosphorylation promoted the translocation of P-gp into caveolae, inducing MDR in gastric cancer SGC7901/Adr and breast cancer MCF-7/Adr cells." (PMID 25788263, 2015). "This study demonstrated the role of endocytic protein caveolin-1 in T-DM1 internalization and improved cytotoxicity in breast cancer cells." (PMID 26172389, 2015). "In this study, we investigated the probable interaction between caveolin-1 and BKCa in MCF-7 breast cancer cells." (PMID 25397596, 2014). "In metastatic breast cancer cells (MDA-MB-231), caveolin-1 is highly expressed and phosphorylated on tyrosine-14, in comparison to non-metastatic cancer cells." (PMID 22505999, 2012). "Therefore, Cav-1 may be expressed only in certain breast cancer subtypes." (PMID 22356861, 2012). "The human breast cancer cell line MDA-MB-231 and DI-TNC1, as well as MEF-3T3 cells, all expressed high endogenous levels of caveolin-1." (PMID 22505999, 2012). "Our findings in both human breast cancer (MDA-MB-231) and mouse melanoma (B16-F10) cells support the notion that caveolin-1 enhances polarization, directional migration and persistency of metastatic cells." (PMID 22505999, 2012). "In contrast, mammary tumors that develop following IGF-IR downregulation and acquire a claudin-low genotype express moderate to high levels of Cav-1 in the tumor cells themselves." (PMID 22356861, 2012).
breast carcinoma (continued). "Lipid rafts and caveolin-1 are required for invadopodia formation and ECM degradation by human breast cancer cells." (PMID 22216126, 2011). "It is important to note that these breast cancer stromal gene lists also includeCxcl12, a known HIF-target gene, that is transcriptionally-upregulated~5-fold in Cav-1 (-/-) stromal cells." (PMID 20442453, 2010). "Results showed higher HER2/neu mRMA levels and lower CAV1 and CAV2 mRMA levels in breast cancer tissues than in corresponding normal tissues (P<0.001)." (PMID 15305200, 2004). "CAV1 and CAV2 protein levels were downregulated in four representative breast cancer tissues compared to corresponding normal breast tissues." (PMID 15305200, 2004). "We then evaluated for correlations between CAV1, CAV2 and HER2/neu gene expression and clinicopathologic factors in the 162 breast cancer cases." (PMID 15305200, 2004). "We examined quantitatively the mRNA levels of CAV1, CAV2 and HER2/neu in 162 cases of breast cancer using real-time PCR." (PMID 15305200, 2004). "In the present study, we investigated the mRNA levels of CAV1, Caveolin-2 (CAV2) and HER2/neu in breast cancer tissues from 162 cases by the real-time PCR to evaluate the clinical significance of these genes." (PMID 15305200, 2004). "Similar to the previously discussed role of CAV1, ATG-related secretory molecules could potentially serve as serodiagnostic markers in breast cancer." (PMID 39893499, 2025). "Future research into Cav‐1‐mediated TGF‐β/Smad signaling could offer valuable insights into the connection between SSc and breast cancer, offering potential strategies for managing these diseases." (PMID 40778471, 2025). "Additionally, PTRF and Cav-1 interact with insulin-like growth factor-I receptor (IGF-IR), regulating its internalization in breast cancer cells that are known to express high levels of IGF-IR." (PMID 39857963, 2025). "Moreover, statistical analysis of gene data from the TCGA database confirmed that the expression trend of CAV1 in breast cancer tissues was consistent with that of CD36, with CAV1 expression significantly lower in cancer tissues compared with normal tissues." (PMID 41267927, 2025). "So, we conclude that CAV1 in BC-derived sEVs promote neutrophil recruitment through the TLR4-NF-κB-IL-6/CCL2 axis and neutrophil N2-type polarization through the TLR4/NF-κB/NLRP3 pathway, thus promoting the lung metastasis of breast cancer." (PMID 39494337, 2024). "Interestingly, compared with CTCs in metastatic patients, the DTCs in the bone marrow of early HER2-positive breast cancer patients presented increased expression of stem cell markers such as ALDH1, CAV1 and VIM." (PMID 36765527, 2023). "Cell lines and primary breast cancers from humans contain negative CAV-1 RNA and protein levels, and CAV-1 reintroduced in vitro inhibits many tumorigenic properties, including anchorage independent growth." (PMID 37496657, 2023). "Evidence suggests that the expression level of Cav-1 in stromal cells is positively correlated with the prognosis of breast cancer patients, but the expression level of Cav-1 in tumors is not indicative of prognostic survival." (PMID 37828916, 2023). "The present results revealed that hATT-CM decreased CAV-1 and increased C/EBPβ-LIP protein expression in adipocytes, further supporting the contention that the breast cancer peritumoral AT could contribute to tumor progression." (PMID 37181035, 2023). "Although stromal Cav1 loss, as discussed, is associated with worse outcomes in women with breast cancer, there have been no published studies to date evaluating the role of stromal Cav1 levels in black women with breast cancer." (PMID 37822942, 2023). "It was found that the reduction in CAV-1 expression was mainly in the stroma of breast cancer, not in breast cancer parenchyma." (PMID 36604141, 2022). "In breast cancer line C4HD cells, caveolin-1 expression is upregulated by progestin." (PMID 35409055, 2022).
breast carcinoma (continued). "In human breast cancer cell line BT474, estrogen increases the expression of Caveolin-1." (PMID 35409055, 2022). "In human breast cancer MCF-7 cells, estrogen inhibits Caveolin-1 synthesis." (PMID 35409055, 2022). "In this study, we present a new mechanic through bioinformatics tool and basic experiments: the HOTAIR/miR-203/CAV1 axis, which complemented the role network of HOTAIR as a ceRNA, thus, it will provide a novel potential idea for breast cancer research and therapy." (PMID 36233075, 2022). "We have previously reported on how the expression of CAV1 and its phosphorylation on tyrosine-14 (pY14-CAV1) promote migration, invasion, and metastasis of colon and breast cancer, as well as melanoma cells lacking E-cadherin." (PMID 35740528, 2022). "Lack of caveolin-1 (Cav-1) signifies the Reverse Warburg Effect; for example, in the stroma of human breast cancer tissue, the lack of Cav-1 was correlated to recurrence and metastasis." (PMID 36361782, 2022). "And there was a co-expression relationship between AC108474.1 and 5 ferroptosis-related genes (TAZ, ISCU, CAV1, PLIN4, and HIC1), including 1 ferroptosis driver, 2 ferroptosis suppressor and 2 ferroptosis marker, and AC108474.1 was a protective factor for breast cancer patients too." (PMID 34164433, 2021). "Low mechanical stress has been shown to activate Caveolin-1, triggering the FAK/Src and ROCK/p-MLC pathways, which are involved in the reorganization of the cytoskeleton, cell motility, focal adhesion dynamics and breast cancer cell adhesion." (PMID 33718218, 2021). "Taken together, ursolic acid, the bioactive compound of Oldenlandia diffusa, could dramatically suppress breast cancer growth and metastasis by impairing glycolytic metabolism via activating SP1/Cav-1 signaling." (PMID 34568078, 2021). "Cav-1 negative tumors show increased tumor progression, metastasis, and estrogen receptor-negative genotype compared to Cav-1 positive breast cancer." (PMID 33614646, 2021). "In this study, we systematically demonstrated that ursolic acid, the bioactive compound of Oldenlandia diffusa, could dramatically suppress breast cancer growth and metastasis by impairing glycolytic metabolism via activating SP1/Cav-1 pathway." (PMID 34568078, 2021). "What is more, SP1 knockdown could partially abrogate the induction effect of ursolic acid on both Cav-1 protein expression and CAV1 promoter activity in breast cancer cells." (PMID 34568078, 2021). "Alternatively, the silencing of PTPN14 in metastatic breast cancer cells that express [MDA-MB-231(shC)] or not CAV1 [MDA-MB-231(shCAV1)] using an esiRNA against PTPN14 increased cell migration, as well as invasion of those MDA-MB-231 cells expressing CAV1." (PMID 32152405, 2020). "It was reported that the 5′ promoter of CAV1 was methylated in human breast cancer cells, whereas not in the normal human mammary epithelial cells." (PMID 32508059, 2020). "Finally, we successfully verified the FVIIa-dependent Cav1 phosphorylation and the importance of Cav1 and ITGβ1 on the anti-apoptotic signaling downstream of TF in MDA-MB-231 breast cancer cells." (PMID 32458278, 2020). "Compared with the nonmalignant mammary epithelial cell line MCF-10A, Cav-1 expression was significantly decreased in multiple human breast cancer cell lines." (PMID 32528105, 2020). "Correlation analysis validated the negative correlation between Cav-1 and c-Myc expression levels (P = 0.001) as well as the negative correlation between Cav-1 and HIF1α expression levels (P = 0.018) in breast cancer patients." (PMID 32528105, 2020). "In the present study, we found that 3-BrPA could induce Cav-1 expression and therefore inhibit the BCSCs self-renewal in RAS-transformed MCF-10A cells and breast cancer MCF-7 cells." (PMID 32528105, 2020).
breast carcinoma (continued). "Consistent with our nystatin data is the intriguing observation that genetic disruption of caveolin-1—an essential component of functional caveolae—in mouse mammary tumor cells was shown to impair the expression of HSP25 but not HSP70." (PMID 32290618, 2020). "Furthermore, CAV1 knockdown inhibits invasion and migration of BT474 breast cancer cells, upregulates E-cadherin and downregulates MMP-2, MMP-9 and MMP-1." (PMID 31362353, 2019). "In addition, Cav-1 and lipid rafts are required for the formation and activity of invadopodia and extracellular matrix (ECM) degradation in human breast cancer cells." (PMID 31759347, 2019). "Alternatively, results from our research group revealed that T47-D cells lacking CAV1 increased their migration and invasion after being exposed to EVs derived from metastatic breast cancer cells with high endogenous levels of CAV1." (PMID 31362353, 2019). "Taraska and collaborators described that EVs from metastatic breast cancer cells with high endogenous CAV1 levels are capable of stimulating migration in non-metastatic breast cancer cells such as MCF7, which coincidently express relatively low levels of CAV1." (PMID 31362353, 2019). "Though subtypes of breast cancer were not well balanced in patients with different tumor Cav-1 expression, the doublet seemed to be equally effective across these molecular subtypes." (PMID 30348118, 2018). "Currently, gene therapy is not a practical way in which to induce overexpression of caveolin-1 in breast cancer patients." (PMID 29500444, 2018). "This study found a negative relationship between CAV1 shore methylation and expression in breast cancer." (PMID 29373959, 2018). "Our study not only uncovers the novel function and mechanisms of ADQ in chemosensitizing breast cancer at least partly via targeting caveolin-1, but also sheds novel light in utilizing network pharmacology in Chinese Medicine research." (PMID 30333750, 2018). "We attempted to study in vitro ADCC upon CAV1 depletion in NCIN87 gastric and BT474 breast cancer cells (T) using peripheral blood mononuclear cells (PBMCs) from healthy donors and engineered Jurkat cells as effector cells (E) that stably express the FcγRIIIa receptor." (PMID 30510281, 2018). "Previous reports have suggested negative correlations of caveolin-1 with human cancers, and recent studies have proved that caveolin-1 inhibits breast cancer cell migration and metastasis." (PMID 29500444, 2018). "We found that TF expression in breast cancer lines and tumors closely clustered with higher levels of EMT (high vimentin/low E-cadherin) and classical basal-type biomarkers KRT5, KRT14 and caveolin-1, while it clustered with lower levels luminal-type biomarkers KRT8, KRT18, ERBB3 and ESR1." (PMID 28938620, 2017). "Inhibition of MEK and pre-treatment with Trolox, both individually precluded CAV1 up-regulation induced by either Methotrexate or Etoposide in colon cancer cell lines HT29(US), DLD-1 and HT29(ATCC), as well as in MCF7 breast cancer cells." (PMID 29340103, 2017). "These CpG islands are not methylated in normal breast epithelial cells that express higher levels of CAV1; however in breast cancer cell lines that do not express CAV1, this region is highly methylated." (PMID 29340103, 2017). "To distinguish between these possibilities, we first evaluated whether the low levels of basal CAV1 expression observed in the colon cancer cells (HT29(US), DLD-1 and HT9(ATCC)) and in the breast cancer cell line MCF7 were attributable to promoter methylation." (PMID 29340103, 2017). "Moreover, in breast cancer cells, activated STAT3 promoted invasion and brain metastasis by suppressing Cav-1 transcription by directly binding to its promoter." (PMID 29221162, 2017).